Y_RNA (Y RNA )
Gene: Miscellaneous RNA gene on chromosome 2 (207,687,960 to 207,688,059, forward strand). Ensembl gene ENSG00000200764.
Homologues: Orthologues: chimpanzee Y_RNA (97% identical), macaque Y_RNA (94% identical). Paralogues in human: RNY3 (90% identical), Y_RNA (89% identical), RNY3P1 (88% identical), Y_RNA (88% identical), Y_RNA (87% identical), Y_RNA (86% identical), Y_RNA (85% identical), RNY3P14 (84% identical), Y_RNA (84% identical), RNY3P2 (83% identical), Y_RNA (83% identical), RNY3P11 (82% identical), and 96 more.